LRRK2 (leucine rich repeat kinase 2)
Diseases named in the same sentence as LRRK2 in open-access papers (continued):
Sharing a sentence is not in itself a finding about the gene and the disease.
Parkinson disease (continued). "The role of non-DA neurons in DA release is especially of interest for Parkinson’s disease genes such as LRRK2, which have relatively low expression in DANs but are enriched elsewhere e.g. in cholinergic interneurons, while still exhibiting DA release deficit phenotypes." (PMID 36864664, 2023). "Lack of protein α-syn and tau aggregation in LRRK2 parkinsonism leaves an open question, and other factors such as gene regulation, immune response, or mitochondrial dysfunction could be at play." (PMID 33494262, 2021). "Leucine-rich repeat kinase 2 (LRRK2), one of the hub genes involved in mitochondrial membrane function, has been reported to play a crucial role in inducing mitochondrial fragmentation by mitochondrial dynamin-related protein-1 (Drp1) in patients with Parkinson’ disease." (PMID 30651404, 2019). "Almost half of our LRRK2 carriers did not report a family history of Parkinson’s disease." (PMID 31324919, 2019). "Pathway enrichment analysis identified 90 significant canonical human pathways, including several pathways more commonly related to non-infectious diseases such as the LRRK2 pathway in Parkinson’s disease, and PD-1/PD-L1 signaling pathway important for new immuno-oncology therapies." (PMID 29321020, 2018). "In this study, we examine whether LRRK2 also interacts with signaling components of the WNT/Planar Cell Polarity (WNT/PCP) pathway, which controls the maturation of substantia nigra dopaminergic neurons, the main cell type lost in Parkinson’s disease patients." (PMID 28697798, 2017). "However, the pathomechanisms linking LRRK2 (G2019S) function to Parkinson’s disease are not yet fully understood." (PMID 27812199, 2016). "Here, we describe the generation and deep-phenotyping of novel LRRK2 BAC transgenic rat models of Parkinson's disease that express either the wild-type or R1441C or G2019S mutant forms of human LRRK2 and develop age-dependent Parkinsonian motor and non-motor symptoms." (PMID 26744332, 2016). "This suggests that the origin of EDS in LRRK2-2 PD is an intrinsic feature of the disease itself related to an abnormal sleep-wake control, and it is not the result of nocturnal sleep abnormalities, parkinsonism, or any drug." (PMID 26177462, 2015). "LRRK2 parkinsonism is clinically indistinguishable from idiopathic PD." (PMID 25061481, 2014). "Our findings highlight the importance of the WD40 domain for LRRK2 function in neurons, and indicate that future studies of the WD40 domain may help to elucidate important features of LRRK2 biology relevant to the pathogenesis of Parkinson's disease." (PMID 20041156, 2009). "Several pathological mutations in the genes coding for PTEN-induced Kinase 1 (PINK1), Parkin, Leucine Rich Repeat Kinase 2 (LRRK2), glucocerebrosidase 1 (GBA1) and DJ-1 or PARK7 (Parkinson disease protein 7) were subsequently reported and established the genetic link to PD." (PMID 40540721, 2025). "Homozygous LRRK2-related Parkinson disease (PD) has been reported and does not appear motorically worse than heterozygous LRRK2 PD, however, descriptions of non-motor features and neuropathology in these cases are limited." (PMID 39175765, 2024). "Importantly, LRRK2-parkinsonism is clinically indistinguishable from idiopathic late-onset PD11." (PMID 37443150, 2023). "In addition, Parkinson’s disease patient monocytes secreted more inflammatory cytokines compared to healthy control, and cytokine expression positively correlated with leucine-rich repeat kinase 2 expression in T cells from Parkinson’s disease but not healthy controls." (PMID 28649611, 2017). "Also, alpha-synuclein, Leucine-rich repeat kinase 2, ubiquitin carboxyl-terminal hydrolase L1, Parkin, Pink1, Grb10-Interacting GYF Protein-2, or Omi/HtrA2, which are implicated in Parkinson's disease, are not included." (PMID 21731734, 2011).
Parkinson disease (continued). "Also, given that LRRK2 is a key player in the pathogenesis of Parkinson’s disease while LRRK1 is not, the comparison of structures of both LRRK proteins may yield clues to LRRK2’s pathological functions and aid in designing novel LRRK2 targeting therapeutics." (PMID 28819229, 2017).
Parkinsonism (206 papers, 2006 to 2026). Characteristic neurologic anomaly resulting from degeneration of dopamine-generating cells in the substantia nigra, a region of the midbrain, characterized clinically by shaking, rigidity, slowness of movement and difficulty with walking and gait. "Compared to non-carriers, the age of disease onset is older for patients with PSP carrying LRRK2 gene mutations (mean: 72.3 years), with the predominant clinical phenotype being parkinsonism, frequently leading to an initial misdiagnosis of PD." (PMID 40722695, 2025). "The final analytic sample included 148 LRRK2-associated parkinsonism cases and a comparator group of 378 sporadic PD CSFasynSAA+ (sPD) frequency matched to them by age and disease duration." (PMID 39108519, 2024). "The novel p.L1795F is consistent with the LRRK2-associated PD phenotype described in the literature, although it is associated with more rapidly progressive parkinsonism and earlier onset of severe motor fluctuations." (PMID 38854119, 2024). "The Parkinson’s imaging cohort includes 119 sporadic patients (idiopathic Parkinson’s disease, iPD), 5 patients with pathogenic mutations of the LRRK2 gene (PD-LRRK2) and 10 patients with pathogenic mutations of the GBA gene (PD-GBA)." (PMID 32792423, 2020). "Induced pluripotent stem cell (iPSC) lines were derived from three PD patients carrying a LRRK2-G2019S heterozygous mutation, and three healthy control individuals, from the Oxford Parkinson’s Disease Centre (OPDC) Discovery Cohort." (PMID 28096185, 2017). "Monogenic forms of the disorder account for up to 10% of parkinsonisms, and mutated parkin and leucine-rich repeat kinase 2 (LRRK2) are responsible for the majority of genetic PD cases." (PMID 22666358, 2012). "Five of the identified genes induce a roughly typical PD presentation [a-synuclein, parkin, PTEN induced putative kinase 1, DJ-1, and leucine-rich repeat kinase 2 (LRRK2)] while mutations of ATP13A2 (PARK9) cause Kufor–Rakeb disease characterized by both Parkinsonism and many atypical features." (PMID 23346074, 2012). "Although LRRK2 kinase inhibitors have proven protective in experimental parkinsonism and have been suggested for clinical translation, the mechanisms by which mutant LRRK2 contributes to PD pathophysiology are not fully understood." (PMID 36759912, 2023). "In LRRK2 parkinsonism, a large proportion of cases with clinically diagnosed PD or PDD also have significant concomitant Alzheimer’s disease pathology with or without LBs (12 out of 15 cases)." (PMID 33494262, 2021). "LRRK2 parkinsonism is broadly similar to “idiopathic” disease in clinical manifestations and age at onset (AAO), generating interest in its potential as a therapeutic target with broader application to PD." (PMID 32873436, 2021). "To confirm whether O-αS-treated LRRK2 G2019S-Tg mice showed early parkinsonism-like behaviors, we evaluated gait performance and motor skill learning which might be affected by early synaptic dysfunction in PD pathogenesis." (PMID 37876795, 2023). "We found that MAP1B interacts with LRRK2 and protects against Parkinsonism, both of which may be therapeutically targeted for the treatment of PD." (PMID 38020716, 2023). "We further demonstrated here that the inhibition of LRRK2 by FL090 effectively prevented parkinsonism in toxin‐related and α‐syn‐mutant mice, highlighting its potential involvement in the pathogenesis of PD without LRRK2 mutations." (PMID 38020716, 2023). "Early onset LRRK2-related PD as well as milder forms of DNAJC6-related Parkinsonism may present with a phenotype resembling pure PRKN/PINK1 recessive cases." (PMID 34630269, 2021). "Thus, our findings reinforce the link between impaired microtubule acetylation in LRRK2 parkinsonism and increased α-tubulin acetylation through inhibiting HDAC6 activity revealed a beneficial effect in mitigating neuronal degeneration in PD." (PMID 33231564, 2020). "Only PD and parkinsonism cases were tested for SNCA and LRRK2 mutations." (PMID 27613114, 2016).
Parkinsonism (continued). "Thus, a strategy to stabilize microtubule integrity or promote cytoskeleton-based cargo trafficking may be beneficial for LRRK2 parkinsonism and promising for PD treatment." (PMID 33231564, 2020).
Crohn disease (106 papers, 2010 to 2026). A gastrointestinal disorder characterized by chronic inflammation involving all layers of the intestinal wall, noncaseating granulomas affecting the intestinal wall and regional lymph nodes, and transmural fibrosis. "For example, the N2081D LRRK2 mutation, linked to increased Crohn’s disease risk, is located in the kinase domain and is thought to enhance kinase activity." (PMID 40867920, 2025). "LRRK2 has previously been implicated in Crohn’s disease through its expression in intestinal epithelial cells, specifically in Paneth cells, where it was shown to be required for anti-microbial peptide lysozyme secretion." (PMID 40394349, 2025). "Crohn’s disease-linked LRRK2 mutations target specific kinase substrates and worsen colitis in a newly developed mouse model." (PMID 41031878, 2025). "Our previous exome-wide association analysis of Crohn’s disease (CD) in individuals of Ashkenazi Jewish descent identified the N2081D coding variant in LRRK2 as a CD risk allele." (PMID 41031878, 2025). "Mutations in Leucine-Rich Repeat protein Kinase 2 (LRRK2) are associated with Parkinson’s disease (PD) and Crohn’s disease (CD), but the regulation of LRRK2 during inflammation remains relatively unexplored." (PMID 40394349, 2025). "LRRK2 has been reported to be associated with the risk of Crohn’s disease in gastrointestinal disorders." (PMID 39006030, 2024). "Mutations in LRRK2 have been implicated in the increased incidence of both PD and Crohn's disease (CD)." (PMID 39500355, 2024). "Although LRRK2 has been identified as the gene most associated with PD, meta-GWAS has also revealed LRRK2 to be a major susceptibility gene for Crohn’s disease (CD)." (PMID 38607004, 2024). "Genome wide associations have found that LRRK2 G2019S mutations are a risk factor for both Crohn’s disease (CD) and PD, with inflammatory processes proposed as common mechanistic pathways." (PMID 39175765, 2024). "The LRRK2 locus includes SNPs that nominate genome-wide associations to several inflammatory disorders (Crohn’s disease [rs11175593_T], inflammatory bowel disease [rs4768236_C], pediatric immune diseases [rs17466626_G], and platelet count [rs529898481_G])." (PMID 39062657, 2024). "Among them, ATG16L1, NOD2, IRGM, and LRRK2 are autophagy-associated genes, which highlights the key role of autophagy in genetic susceptibility of Crohn's disease." (PMID 39883213, 2024). "A SNP (rs3761863) in LRRK2 has been found to be significantly associated with Crohn's disease susceptibility." (PMID 39883213, 2024). "LRRK2 variants were shown to modulate the risk for Crohn’s disease, a chronic inflammatory bowel disease, and LRRK2 kinase activity was shown to influence microglial activation and pro-inflammatory cytokine production." (PMID 39726830, 2024). "Mutations in the leucine-rich repeat kinase 2 (LRRK2) gene are the most common genetic cause of Parkinson's disease (PD), with growing importance also for Crohn's disease and cancer." (PMID 37454104, 2023). "Crohn’s disease is associated with PD, since both diseases shared a common genetic risk factor, leucine-rich repeat kinase 2 (LRRK2), as discovered in genome-wide association studies." (PMID 38097625, 2023). "LRRK2 has been implicated in inflammation because LRRK2 gene variants are linked to autoimmune diseases, such as Crohn’s disease and systemic lupus erythematosus." (PMID 36671564, 2023). "Leucine-rich repeat kinase 2 (LRRK2) variants associated with Parkinson’s disease (PD) and Crohn’s disease lead to increased phosphorylation of its Rab substrates." (PMID 37874617, 2023). "For example, LRRK2 p.N2081D has been implicated as a shared risk variant in Crohn's disease, and independent LRRK2 5' variation has been shown to be a modifier of progressive supranuclear palsy phenotypes." (PMID 34542912, 2022).
Crohn disease (continued). "Genome‐wide association studies have connected LRRK2 locus polymorphisms with increased risk of immune diseases such as systemic lupus erythematosus, Crohn's disease, and inflammatory bowel disease and with susceptibility to multibacillary leprosy." (PMID 36051080, 2022). "It has been noted that LRRK2 is far more highly expressed in immune cells than neurons, and is also linked to Crohn’s disease, an inflammatory bowel disorder, a class of disorders associated with PD83." (PMID 35314697, 2022). "All of the most common PD‐linked mutations are found in the carboxy‐terminal half of LRRK2, as well as a mutation that has been linked to Crohn's disease, which also increases LRRK2's kinase activity." (PMID 34423856, 2021). "A single nucleotide polymorphism (N2081D) in the region encoding the kinase domain of LRRK2 is a major risk factor for Crohn’s disease, a form of inflammatory bowel disease." (PMID 34201785, 2021). "Recently it was shown that PD patients share a LRRK2 risk variant, N2081D, and a protecting variant, N551K, with Crohn’s disease, CD, patients." (PMID 33584195, 2021). "Common genetic variation in LRRK2 modifies susceptibility to immunological disorders including Crohn’s disease and leprosy." (PMID 33672296, 2021). "Large multi-center whole exome, WES, -studies have shown that the LRRK2 gene is associated with several chronic inflammatory disorders, including Crohn’s disease and leprosy." (PMID 33584195, 2021). "The LRRK2 gene is associated with several chronic inflammatory disorders, including Crohn’s disease and leprosy but these results have originated from vast genetic studies like GWAS in heterogenous PD populations." (PMID 33584195, 2021). "Crohn’s disease and PD share two genetic risk factors for inflammation: LRRK2 risk alleles and a NOD2 mutation in a protein encoded by CARD15." (PMID 32575365, 2020). "Multiple single-nucleotide polymorphisms (SNPs) in the LRRK2 locus also have been reported to be associated with inflammatory diseases including Crohn’s disease (CD)." (PMID 32180132, 2020). "Mutations and single‐nucleotide polymorphisms in the kinase leucine‐rich repeat kinase 2 (LRRK2) are associated with an increased risk of Parkinson's disease (PD) or Crohn's disease." (PMID 32643832, 2020). "A recent study has identified the mutated LRRK2 gene through exome sequencing of patients with Crohn’s disease (CD) and ulcerative colitis (UC), which indicates that LRRK2 mutations are associated with intestinal inflammatory disorders." (PMID 32422864, 2020). "Mutations in LRRK2 are the most common cause of familial Parkinson’s disease (PD) and are also implicated in Crohn’s disease." (PMID 33122997, 2020). "Genome wide association studies analyses revealed that LRRK2 polymorphisms are not only associated with PD, but also other disorders including Crohn’s disease and Leprosy pointing out the importance of the immune functions of LRRK2." (PMID 33013290, 2020). "Some functional variants in LRRK2 gene influencing the disease risk are shared between Crohn’s disease and PD." (PMID 32256311, 2020). "Intriguingly, LRRK2-5′AS has a strong linkage to autoimmune diseases, in particular Crohn’s disease and multiple sclerosis, and its expression is associated to neutrophils." (PMID 30610612, 2019). "Variants in both MUC19 and LRRK2 have been reported together in multiple GWAS investigating Crohn’s disease, ankylosing spondylitis, and autoimmune thyroid disease." (PMID 30861027, 2019). "Of note, LRRK2 has also been genetically implicated in several immunological disorders, namely inflammatory bowel diseases (IBDs), including Crohn’s disease and ulcerative colitis, Hansen’s disease (leprosy), and systemic lupus erythematosus." (PMID 32714591, 2018).